PIK3CA (phosphatidylinositol-4,5-bisphosphate 3-kinase catalytic subunit alpha)
Diseases named in the same sentence as PIK3CA in open-access papers (continued):
Sharing a sentence is not in itself a finding about the gene and the disease.
breast cancer (continued). "Moreover, TNBC and other breast cancer subtypes have a high frequency of AKT3 amplifications, PIK3CA amplifications and mutations." (PMID 36139513, 2022). "These values are consistent with plasma versus tissue PPA estimates for FDA‐approved plasma CDx assays, such as Therascreen® PIK3CA RGQ PCR Kit [54.6%; breast cancer (alpelisib)] and cobas® EGFR Mutation Test v2 [≥58.7%; NSCLC (erlotinib, osimertinib, gefitinib)]." (PMID 35338679, 2022). "Therefore, the optimization of PIK3CA molecular analysis in breast cancer FFPE samples, either primary or metastasis, is a prerequisite for the implementation of this test and its integration with liquid biopsies." (PMID 36428975, 2022). "Now, it is being tested in HER2 positive MBC with PIK3CA mutations in multiple clinical trials and emerging results will guide us to deal with HER2 positive breast cancer with PIK3CA mutations (ClinicalTrials.gov Identifier: NCT05063786, NCT05230810, NCT04208178)." (PMID 36029565, 2022). "A mutation of PIK3CA is in 25–40% of ER+, HER2− breast cancers, and in 8% of ER- breast cancer." (PMID 36291916, 2022). "Although we have not evaluated the effect of PIK3CA helical domain mutation on PEPDG278D activity in CRC cells, we previously showed that PIK3CA helical domain mutation does not confer resistance to PEPDG278D in HER2-positive breast cancer cells." (PMID 35650607, 2022). "However, in non-ACC SGC, the evidence level is 3a based on the efficacy of PIK3CA inhibitors in breast cancer." (PMID 35267442, 2022). "Moreover, mutations in the PIK3 catalytic subunit alpha (PIK3CA) gene, which occur in approximately 40% of patients with HR-positive, HER2-negative breast cancer, predict worse survival outcomes." (PMID 35348782, 2022). "Furthermore, knockdown of p85β reduced cell proliferation and colony formation of PIK3CA E545K mutant MDA-MB361 breast cancer cells and PIK3CA E542K mutant SW948 cells." (PMID 35418124, 2022). "Whole-exome sequencing by The Cancer Genome Atlas (TCGA) program has confirmed earlier work, showing that gain of function mutations in PIK3CA and AKT1, and inactivating mutations in PTEN are common in ER+ breast cancer (32–49%, 13–24%, and approximately 7% respectively)." (PMID 36046843, 2022). "Interestingly, PIK3CA mutations, which were the top mutation in BRCA1-negative and unspecified breast cancer, were found in the lower frequencies of 13.33–16.67% and were not among the top mutated genes in the BRCA1-positive group." (PMID 36298462, 2022). "Patients with hormone receptor (HR)-positive, human epidermal growth factor receptor 2 (HER2)-negative breast cancer have PIK3CA mutations in about 40% of cases." (PMID 35586863, 2022). "Approximately 40% of hormone receptor (HR)-positive, human epidermal growth factor receptor 2 (HER2)-negative breast cancers carry PIK3CA mutations." (PMID 35307037, 2022). "Comparably high mutation rates of PIK3CA are observed in breast carcinomas but have so far not been detected in other types of cancer." (PMID 36443295, 2022). "Examples include inhibitors of EGFR and ALK in lung cancer, or ERBB2 and PIK3CA in breast cancer." (PMID 34006291, 2021). "The PIK3CA gene, coding for a subunit of the catalytic domain of PI3K, is often mutated or amplified in breast cancer, and therapeutic inhibition of this pathway has shown some promising results in some types of breast cancer." (PMID 34809697, 2021).
breast cancer (continued). "The most common grade 3/4 AEs in the overall 58 expansion-phase patients (including the triplet therapy cohort and HR+ HER2− PIK3CA unselected cohort and an ER-negative PIK3CA mutant breast cancer or other solid tumor cohort) were neutropenia (53%) and leukopenia (21%)." (PMID 34769309, 2021). "Similarly, MK-2206 is unlikely to add further benefit to the efficacy of anastrozole alone in a phase II study based on PIK3CA-mutant ER+ breast cancers (NCT01776008)." (PMID 34298731, 2021). "While PIK3CA mutations were identified in the tumor tissue of 47% of patients with localized breast cancer, no mutations were detected in the matched ctDNA." (PMID 34359713, 2021). "Therefore, further large-scale studies investigating thee PIK3CA/Akt/PTEN pathway in canine mammary tumors are necessary." (PMID 34359206, 2021). "Thus, we tested the response of 2 different HER2+PIK3CA-mutant breast cancer PDXs to paclitaxel and 4 different HER2-targeting agents (lapatinib, T-DM1, trastuzumab, and pertuzumab)." (PMID 33886505, 2021). "The current study also revealed that the PIK3CA H1047R mutation is a relatively frequent event in canine mammary tumors, and this mutation was mostly not correlated with downstream molecule expressions or histopathological/clinical features." (PMID 34359206, 2021). "However, our analysis did not identify a number of known mutational cancer drivers, for example, CTNNB1 in hepatocellular carcinoma, PIK3CA in breast cancer and NFE2L2 in lung squamous cell carcinoma." (PMID 34313788, 2021). "Finally, BYLieve supports the notion that the PIK3Ca inhibitor alpelisib is a reasonable treatment option in patients with PIK3Ca mutant luminal breast cancer progressing on CDK4/6-inhibitor therapy." (PMID 33520003, 2021). "Moreover, high PIK3CA mRNA expression was observed in head and neck cancer, breast cancer, colorectal cancer, lung squamous cell carcinoma, and gastric cancer." (PMID 34367282, 2021). "There were 11 PIK3CA-mutant breast cancer cell lines in the DRIVE dataset, with 4 harboring the canonical p.H1047R mutation, 2 p.E545K, 1 p.E542K, 2 p.C420R and 2 rare mutations of unknown significance." (PMID 34313788, 2021). "PIK3CA mutations can co-occur with activating mutations in RTKs such as EGFR, KRAS, and ALK in lung adenocarcinomas, as well as with the loss of PTEN in endometrial and breast cancer." (PMID 33809714, 2021). "Therefore PIK3CA-mutant ER+ breast cancers, which exhibit increased INPP4B expression, display a gene expression profile consistent with increased Wnt/β-catenin signaling." (PMID 34035258, 2021). "PIK3CA and AKT1 gene mutations are common in breast cancer, and PIK3CA mutation is usually found in ER-positive and HER-2 positive breast cancer." (PMID 34552932, 2021). "PIK3CA and AKT1 gene mutations are observed in numerous types of cancers, including breast cancer." (PMID 33669698, 2021). "The PI3Kα-specific inhibitor alpelisib, has shown activity in PIK3CA-mutant breast cancers (NCT02437318) and recently granted FDA and European commission approval, while its potential in the regression and stabilisation of progressive BCBM has been highlighted." (PMID 34499316, 2021). "Copy number (CN) alterations in ctDNA were also associated with breast cancer subtype, with CN alterations in MYC, PIK3CA, EGFR, CCNE1, CDK6, BRAF and MET more common in TNBC (q = 0.01, q < 0.0001, q = 0.001, q < 0.0001, q = 0.0003, q = 0.0002 and q = 0.01, respectively)." (PMID 33893289, 2021). "Therascreen PIK3CA RGQ PCR kit, another PCR-based assay, was approved for the assessment of PIK3CA mutations in plasmatic cfDNA collected from patients affected by advanced hormone receptor-positive HER2-negative breast cancer." (PMID 34298675, 2021).
breast cancer (continued). "An initial phase I clinical trial demonstrated clinical activity of taselisib in patients with advanced solid tumors, particularly in breast cancers with PIK3CA genetic alterations, with an overall response of 36% compared to no response in patients with wild-type PIK3CA." (PMID 34298731, 2021). "Indeed, while HSP70 knockdown led to senescence in breast cancer cell lines expressing PIK3CA, HER2 or RAS oncogenes, normal human breast epithelial cell line MCF10A was resistant to HSP70 knockdown." (PMID 34943954, 2021). "We also examined the expression of these genes in a separate cohort of 698 luminal (ER/PR+) breast cancers using the TCGA dataset, where PIK3CA-mutant cancers displayed significantly higher expression of eight Wnt genes (LEF1, TCF7L1, TCF7L2, CTNNB1, LRP6, SFRP2, WNT5A, and MSX2)." (PMID 34035258, 2021). "These dissimilarities may suggest that different mammary tumorigenic mechanism in humans and dogs, for example, activation of Akt may be PIK3CA-independent in canine mammary tumors, possibly phosphorylated by tyrosine or serine/threonine kinases." (PMID 34359206, 2021). "Based on SOLAR-1, alpelisib in combination with fulvestrant may be of clinically beneficial for ER+ and PIK3CA mutant breast cancer." (PMID 33632156, 2021). "The clinical significance of PIK3CA amplification remains unclear, and clinical trials enrolling PIK3CA amplified breast cancers are ongoing." (PMID 33632156, 2021). "PIK3CA and AKT isoforms are frequent targets of mutations/amplification in breast cancer." (PMID 33498407, 2021). "The addition of MK-2206 to anastrozole did not demonstrate a significant benefit to ERα+ breast cancer patients with PIK3CA mutations." (PMID 33498407, 2021). "The fact that PIK3CA mutations and PTEN loss are nearly mutually exclusive implies that deregulated PIP3 is critical for tumorigenesis in breast cancers and that loss of PIP3 homeostasis by abrogation of either PIK3CA or PTEN relieves selective pressure for targeting of the other gene." (PMID 34298731, 2021). "The PIK3CA pathway is the most common activated pathway in breast cancer." (PMID 33673133, 2021). "In a clinical trial (I-SPY TRIAL, NCT01277757), MK-2206 is currently tested in combination with or without trastuzumab for treatment of advanced breast cancer with PIK3CA or AKT mutations, and/or PTEN loss/PTEN mutation." (PMID 34298731, 2021). "In order to extend the knowledge, we assessed the prevalence of the E542K, E545K, H1047R mutations within the PIK3CA gene and the E17K mutation within the AKT1 gene, and the expression of the PIK3CA, PIK3R1, PTEN, AKT1, mTOR genes in a cohort of patients with breast cancer." (PMID 33669698, 2021). "Although Hrs knockdown did not affect the size or weight of GFP-vector tumors, the enhanced growth of GFP-INPP4B tumors was suppressed by Hrs depletion, indicating that INPP4B promotes the proliferation and tumor growth of PIK3CA-mutant ER+ breast cancer cells in an Hrs-dependent manner." (PMID 34035258, 2021). "The prognosis of breast cancer patients with PIK3CA mutations has been reported to be better than that of patients without PIK3CA mutations." (PMID 34012039, 2021). "AA supplementation or Rlip inhibitors combined with PIK3CA inhibitors recently approved for Her2-negative breast cancer treatment could expand the utility of these drugs for Her2-amplified breast cancer as well." (PMID 34944997, 2021). "In our study, PIK3CA mutation status does not appear to have prognostic value, as in non-inflammatory early breast cancer, or predictive value, but no definite conclusion can be formulated given the small number of patients with mutations." (PMID 34911971, 2021). "Interestingly, PIK3CA-mutant ER+ breast cancers display minimal AKT activation and little dependence on AKT signaling compared to tumors with other PI3K pathway alterations, such as PTEN loss." (PMID 34035258, 2021).
breast cancer (continued). "Phosphoproteomic analysis informed the translational outcomes of PIK3CA mutations in breast cancer, which often are not correlated with the transcriptional signature of breast tumors." (PMID 33669749, 2021). "In HER2+ breast cancer, mutations in PIK3CA are linked with poor prognosis not only in the advanced but also in the early setting." (PMID 34298731, 2021). "Interestingly, high PIK3CA mRNA level was also observed in breast cancer, colorectal cancer, head and neck cancer, lung squamous cell carcinoma, and gastric cancer." (PMID 34367282, 2021). "PIK3CA mutations are detected in more than one third of HR-positive breast tumors (34.5%) and less frequently in HER2-overexpressing tumors (22.7%), whereas the incidence drops to 8.3% in triple-negative and basal-like breast cancer." (PMID 34676052, 2021). "We suggest that dysregulation of PI3K/Akt/PTEN pathway components is a feature in canine mammary tumors, but not directly associated with PIK3CA H1047R mutation except for the expression of PTEN." (PMID 34359206, 2021). "The PIK3CA (phosphatidylinositol-4,5-bisphosphate 3-kinase catalytic subunit alpha) gene encoding the phosphatidylinositol-3-kinase (PI3K) catalytic subunit p110-alpha is commonly mutated in breast cancer." (PMID 34453076, 2021). "In many solid tumor malignancies, including breast cancer, lung, head and neck cancer, and melanoma, increased activity within the PI3K pathway occurs through activating mutations and gene amplifications in PIK3CA (PI3K-α), or loss of expression of the PI3K tumor suppressor, PTEN." (PMID 34512641, 2021). "Effect of PIK3CA mutation to expression of downstream molecules has never been investigated in canine mammary tumors." (PMID 34359206, 2021). "find that imaging of hyperpolarized [1-13C]pyruvate metabolism allows early detection of response and resistance to PI3Kα inhibition in PIK3CA-mutant ER+ breast cancer, which could be used clinically to guide treatment." (PMID 32976773, 2020). "PIK3CA was the most frequent alteration in HER2-positive breast cancer, in 178/185 (96.2%) cases." (PMID 32983983, 2020). "However, the PIK3CA inhibitor is still in the clinical trials and is mostly used in breast cancer, so the clinical evidence for other tumors needs to be furthermore confirmed." (PMID 32508051, 2020). "Notably, the expression of CD44 was positively correlated with estrogen receptor (ER) activity in PIK3CA-mutant breast cancers, and ER-dependent transcription upon PI3Kα pathway inhibition was in turn mediated by CD44." (PMID 33024087, 2020). "PIK3CA was also the most frequent alteration in HER2-positive breast cancer." (PMID 32983983, 2020). "The EFM19 (ER+/HER2−; PIK3CA mt) breast cancer cell line was conditioned through long-term exposure to increasing concentrations of palbociclib until the cells continued to proliferate in the presence of drug at concentrations greater than the cellular IC50 (78 nmol/L)." (PMID 32795346, 2020).
breast cancer (continued). "A blinded set of 25 breast cancer patient FFPE tissue biopsy samples was tested using our in-house triplex dPCR assays without enrichment to detect PIK3CA mutations in exon 9 (E542K, E545K) and exon 20 (H1047L, H1047R)." (PMID 33051521, 2020). "Analysis of the METABRIC dataset showed that increased FOXM1 expression correlates with poorer survival in PIK3CA mutant breast cancer patients, and that breast cancer-specific survival rate is decreased in ER+ breast cancer patients with FOXM1 copy number gain." (PMID 32976773, 2020). "PIK3CA encodes the p110α catalytic subunit of PI3K, and is the most frequently altered oncogene in human cancers, including endometrial, ovarian, colorectal, and breast cancers." (PMID 32106627, 2020). "Breast cancer having PIK3CA mutations can be treated using PIK3CA inhibitors, in hormone receptor-positive HER2 negative subtypes." (PMID 33166334, 2020). "PIK3CA activating mutations and PTEN loss of expression may contribute to treatment resistance in breast cancer (BC)." (PMID 32042320, 2020). "Are pathogenic PIK3CA gene mutations associated with poor clinical outcomes (not living disease-free) for breast cancer?" (PMID 33391340, 2020). "In addition, patients with a higher level of PIK3CA mutant detected by plasma ctDNA in breast cancer showed a worse prognosis." (PMID 32629823, 2020). "Combination therapy with small-molecule inhibitors of AKT and HER2 was conducted in HER2+ breast cancer cell lines with or without PIK3CA mutations, which lead to constitutive activation of the PI3K pathway." (PMID 33303839, 2020). "The therascreen PIK3CA mutation assay and the alpha-specific PI3K inhibitor alpelisib are FDA-approved for identifying and treating patients with advanced PIK3CA-mutated (PIK3CAmut) breast cancer (BC)." (PMID 32404150, 2020). "IGF1 and IGF2 are overexpressed in PIK3CA-mutant breast cancer, which may activate IGF-IR signaling." (PMID 32493414, 2020). "The prognostic impact of PIK3CA genotype on breast cancer outcome is highly debated." (PMID 32210163, 2020). "Given that the PI3K pathway alterations have a high impact in patients with ER+/HER2+ breast cancer, we first evaluated cell viability using ER+/HER2+ breast cancer cell lines with or without PIK3CA mutations." (PMID 33303839, 2020). "In addition, the presence of PIK3CA mutations and/or PTEN loss have been associated with trastuzumab resistance in HER2-positive breast cancers." (PMID 33375706, 2020). "However, elevated expression of PIK3CA has been reported in various types of cancer including oesophageal squamous cell carcinoma, colorectal and breast cancer where was related to invasiveness, metastasis and poor prognosis." (PMID 33273537, 2020). "Indeed, PIK3CA mutations are frequent in breast cancer, occurring in 28–47% of hormone receptor-positive breast cancers, 25% of HER2-positive breast cancers, and 8% of basal-like tumors." (PMID 32391382, 2020). "Overall, the prognostic significance of PIK3CA alterations in breast cancer remains inconclusive." (PMID 32697890, 2020).